TRIM21 (tripartite motif containing 21)
Diseases named in the same sentence as TRIM21 in open-access papers (continued):
Sharing a sentence is not in itself a finding about the gene and the disease.
lung adenocarcinoma (2 papers, 2024 to 2026). A carcinoma that arises from the lung and is characterized by the presence of malignant glandular epithelial cells. "Overexpression of TRIM21 reduced the promoting effect of ZSWIM1 on the proliferation, migration, and invasion of lung adenocarcinoma cells, and reversed the impact of ZSWIM1 on the expression of E-cadherin and Vimentin." (PMID 38880921, 2024).
myocarditis (2 papers, 2018 to 2022). Myocarditis is a condition that is characterized by inflammation of the heart muscle (myocardium). "In accordance with that, cardiac and pancreatic CVB3 replication as well as virus-induced pancreatic acinar cell necrosis and myocarditis were significantly aggravated in TRIM21 deficient mice." (PMID 30410495, 2018). "In this study, we try to explore the role of TRIM21 in the susceptibility of mice to CVB3 induced myocarditis." (PMID 30410495, 2018). "We also demonstrate the antiviral effect of systemic TRIM21 in vivo which leads to the increased resistance to CVB3-induced myocarditis and pancreatic injury." (PMID 30410495, 2018). "Consistently, histological analysis revealed that mice with mock plasmids developed severe myocarditis with diffuse inflammation and necrotic lesions, whereas TRIM21 treatment attenuated myocarditis with restricted inflammation and necrosis." (PMID 30410495, 2018). "We speculate that TRIM21 inhibits CVB3 induced myocarditis by serving as positive regulator in type I IFN production pathway, while TRIM18 promotes myocarditis induced by CVB3 through negatively regulating type I IFN production in antiviral innate immunity." (PMID 35909127, 2022). "While TRIM21 deficient mice exhibited a decreased IFN-β production, an increased cardiac and pancreatic CVB3 replication, and aggravated pancreatic injury as well as myocarditis during acute infection." (PMID 30410495, 2018). "Therefore, groups of mice were retro-orbitally injected with 50 μg TRIM21-plasmids or vector-plasmids using in vivo-Jet PEI reagent 2 days before and 1 day after CVB3 infection, and susceptibility to CVB3 myocarditis as well as viral replication were evaluated in a course of 7 days infection." (PMID 30410495, 2018). "Here, we investigate the antiviral activity of TRIM21 against CVB3 replication and its role in CVB3-induced acute vial myocarditis and pancreatic injury." (PMID 30410495, 2018). "Our results indicate that TRIM21 inhibits CVB3 replication via interacting with MAVS for promoting the K27 polyubiquitination of MAVS, thereby enhancing IRF3-mediated type I IFN signaling pathway and protecting mice against CVB3-induced myocarditis as well as pancreatic acinar cell necrosis." (PMID 30410495, 2018).
oral lichen planus (2 papers, 2023 to 2024). Oral lichen planus is a chronic inflammatory oral condition of unknown aetiology characterized by T-cell-mediated chronic immune response and abnormal epithelial keratinization cycle. "Conversely, TRIM21 binds to ubiquitinated NF-κB through K63 in CD3+T cells in Oral lichen planus (OLP) tissue, resulting in a heightened release of pro-inflammatory factor in T cells, subsequently triggering the NF-κB signaling pathway and exacerbating tissue damage." (PMID 39165359, 2024).
Oral ulcer (2 papers, 2013 to 2024). Erosion of the mucous mebrane of the mouth with local excavation of the surface, resulting from the sloughing of inflammatory necrotic tissue. "Similarly to cytopenia, oral ulcers and Raynaud's phenomenon were also found to be positively, although not significantly, associated with anti-Ro52/TRIM21." (PMID 24294139, 2013).
pancreatic adenocarcinoma (2 papers, 2022 to 2025). "Therefore, this study aims to elucidate how hypoxia regulates ID1 expression in pancreatic adenocarcinoma (PAAD), with a specific focus on post-translational modifications mediated by the E3 ubiquitin ligase TRIM21." (PMID 40919143, 2025).
rhabdomyosarcoma (2 papers, 2022 to 2024). A rare aggressive malignant mesenchymal neoplasm arising from skeletal muscle. "The study next investigated the relationship between TRIM21 expression and the clinical features of rhabdomyosarcoma (RMS)." (PMID 38702792, 2024). "Previous research has reported that the TRIM21 E3 ubiquitination ligase mediates the degradation of SAMHD1 to facilitate EV71 infection of rhabdomyosarcoma RD cells and 293 T cells." (PMID 35803902, 2022).
Stroke (2 papers, 2019 to 2023). Sudden impairment of blood flow to a part of the brain due to occlusion or rupture of an artery to the brain. "A study reported that stroke was associated with cognitive impairment and dementia in older adults, and the six RNA-binding protein (RBP) genes (POLR2F, DYNC1H1, SMAD9, TRIM21, BRCA1, and ERI1) might participate in the process by mediating the hypoxic responses and angiogenesis." (PMID 37006557, 2023).
tauopathies (2 papers, 2024 to 2025). "Both TRIM21 and MYCBP2 are abundant forms of E3 ligases, although their roles in tauopathies remain obscure." (PMID 39974971, 2025). "That particular study showed that a tau-clearing antibody became ineffective in tauopathy mice lacking TRIM21." (PMID 38816762, 2024).
ZIKV infection (2 papers, 2018 to 2025). "While it is novel and insightful to identify TRIM21 and TRIM14 as antiviral factors during LGTV and ZIKV infection, we acknowledge certain limitations in our findings." (PMID 40431659, 2025). "Further characterizations showed that TRIM21 and TRIM14 act as restriction factors against ZIKV and LGTV, while TRIM38 hinders ZIKV infection." (PMID 40431659, 2025).
acute kidney injury (1 paper, 2024). Sudden and sustained deterioration of the kidney function characterized by decreased glomerular filtration rate, increased serum creatinine or oliguria. "TRIM21 ubiquitination degrades GPX4 to promote ferroptosis in acute kidney injury." (PMID 38542289, 2024).
acute monocytic leukemia (1 paper, 2020). Acute monoblastic leukemia (AML-M5), is one of the most common subtypes of acute myeloid leukemia (AML) that is either comprised of more than 80% of monoblasts (AML-M5a) or 30-80% monoblasts with (pro)monocytic differentiation (AML-M5b). "To investigate the impact of TRIM21‐mediated degradation of SAMHD1 on HIV‐1 infection, we employed THP‐1 cells, a human cell line derived from the peripheral blood of an acute monocytic leukemia patient that can be differentiated with phorbol esters (PMA)." (PMID 31797533, 2020).
atherosclerosis (1 paper, 2025). A disease characterized by the build-up of fatty material and calcium deposition in the arterial wall resulting in partial or complete occlusion of the arterial lumen. "Taken together, the activation of the MAPK6‒TRIM21 ubiquitin‒proteasome complex in ECs following DSS stimulation promotes atherosclerosis by regulating endothelial inflammation through the EGR1/CXCL12 axis." (PMID 39763069, 2025).
avian influenza (1 paper, 2023). Infection of domestic and wild fowl and other birds with influenza A virus. "Moreover, the amino acid sequence M1 proteins, mainly from avian influenza such as H5N1, H7N9, H9N2, ranging from 1918 to 2022, reveals a gradual dominant accumulation of the TRIM21-driven R95K mutation when the virus jumps into mammals." (PMID 37343022, 2023).
cerebellar degeneration (1 paper, 2022). Degeneration of the cerebellum. "An autopsy showed high Ro52/TRIM21 expression in the Purkinje cells in the histological sections of the cerebellum in a patient with cerebellar degeneration." (PMID 36611306, 2022).
Cerebral ischemia (1 paper, 2026). Restriction of arterial blood supply to the brain associated with insufficient oxygenation to support the metabolic requirements of the tissue. "TRIM21 deficiency alleviated cerebral ischemia/reperfusion (I/R) injury by attenuating the inflammatory responses and oxidative stress." (PMID 41852809, 2026). "Moreover, MDA5 overexpression effectively reversed protective effects of TRIM21 deficiency after cerebral ischemia." (PMID 41852809, 2026).
chronic kidney disease (1 paper, 2026). Impairment of the renal function secondary to chronic kidney damage persisting for three or more months. "We found that Trim21 is upregulated in the tubular cells of fibrotic kidneys from both chronic kidney disease (CKD) patients and mouse models." (PMID 42129148, 2026).
cornea infection (1 paper, 2022). "As in the cornea, TRIM21 expression was significantly elevated in the TG following cornea infection." (PMID 35336995, 2022).
Dengue hemorrhagic fever (1 paper, 2023). A serious condition caused by Dengue virus infection. "Our findings are consistent with a recent study that showed that the expression of TRIM21 was upregulated in helper innate lymphoid cells of patients with dengue hemorrhagic fever." (PMID 36595532, 2023).
Flavivirus Infections (1 paper, 2025). Infections with viruses of the genus FLAVIVIRUS, family FLAVIVIRIDAE. "From the screening, we identified the TRIM38, TRIM21, and TRIM14 proteins, which were enriched during flavivirus infection." (PMID 40431659, 2025). "To identify the role of TRIM38, TRIM21, and TRIM14 proteins during flavivirus infection, we made polyclonal A549 cells overexpressing these TRIMs." (PMID 40431659, 2025). "Altogether, these data suggest that TRIM38, TRIM21, and TRIM14 are ISGs that mediate the IFN-I response against flavivirus infection." (PMID 40431659, 2025).
Glucose intolerance (1 paper, 2023). Glucose intolerance (GI) can be defined as dysglycemia that comprises both prediabetes and diabetes. "The protective effect of TRIM21 overexpression on HFD-induced glucose intolerance and insulin resistance was partially abolished by PEPCK1 or FASN overexpression." (PMID 37249651, 2023). "In contrast, the knockdown of TRIM21 promotes glucose intolerance, insulin resistance, and triglyceride accumulation." (PMID 37249651, 2023). "Together, these results demonstrated that overexpression of hepatic TRIM21 attenuates glucose intolerance and insulin resistance in obese diabetic mice." (PMID 37249651, 2023). "Moreover, TRIM21 mediated alleviation of hepatic lipid deposition and improvement of insulin resistance and glucose intolerance was partially abolished in the presence of FASN." (PMID 37249651, 2023). "Furthermore, PEPCK1 overexpression partially abolished the protective effect of TRIM21 overexpression on HFD-induced hepatosteatosis, insulin resistance, and glucose intolerance, consistent with PEPCK1 function in gluconeogenesis." (PMID 37249651, 2023).
head and neck cancer (1 paper, 2021). A primary or metastatic malignant neoplasm affecting the head and neck. "Therefore, in this study, we evaluated the expression of TRIM21 in head and neck cancer based on TCGA database." (PMID 34220328, 2021).
HIV-1 infection (1 paper, 2015). The type species of lentivirus and the etiologic agent of acquired immunodeficiency syndrome (AIDS). "A chimeric protein composed of rhesus macaque-derived TRIM5α and human-derived TRIM21 has been shown to potently inhibit HIV-1 infection." (PMID 25884674, 2015).
hypercoagulation (1 paper, 2022). "The upregulation of TRIM21 and BRCA1 and the downregulation of POLR2F were related to platelet activation and increased coagulation, thus suggesting that an imbalance among these genes may result in a state of hypercoagulation, which could easily lead to an ischemic cerebral infarction." (PMID 36118697, 2022).
hypopharyngeal tumor (1 paper, 2024). "TRIM21 as the E3 ubiquitin ligase TRIM21 may be related to hypopharyngeal tumor cell differentiation." (PMID 38313020, 2024).
influenza infection (1 paper, 2026). "This graded activity of TRIM21, which leads to both suppression and promotion of influenza replication, couples linkage-specific ubiquitination of viral nucleoprotein with modulation of innate immune signaling." (PMID 41889827, 2026). "Here, we show that TRIM21 regulates influenza infection in an expression-dependent manner by functioning as a molecular rheostat rather than a binary restriction factor." (PMID 41889827, 2026).
intestinal cancer (1 paper, 2025). "This study discovered a reduction of TRIM21 expression in intestinal cancer tissues compared to para-cancerous tissues." (PMID 39890802, 2025).
leukemia (1 paper, 2022). A malignant (clonal) hematologic disorder, involving hematopoietic stem cells and characterized by the presence of primitive or atypical myeloid or lymphoid cells in the bone marrow and the blood. "Further, we demonstrate that HHT induces autophagic degradation of the CDK2 protein via tripartite motif 21 (Trim21) in cancer cells, which is confirmed in a leukemia mouse model and in human primary leukemia cells." (PMID 35595767, 2022).
lipid metabolic disorders (1 paper, 2023). "The results of this study support the concept that TRIM21 improves hepatic glucose and lipid metabolic disorders through its binding to PEPCK and FASN." (PMID 37249651, 2023). "Firstly, overexpression of TRIM21 improved hepatic insulin sensitivity and ameliorated systemic glucose and lipid metabolism disorders." (PMID 37249651, 2023). "To investigate whether PEPCK1 and FASN were involved in the suppressive effect of TRIM21 on hepatic glucose and lipid metabolic disorders, we injected Ad-PEPCK1 and/or Ad-FASN into HFD-fed mice with TRIM21 overexpression." (PMID 37249651, 2023).
lipoma (1 paper, 2023). A benign, usually painless, well-circumscribed lipomatous tumor composed of adipose tissue. "Mechanistically, UBE2S cooperated with tripartite motif containing 21 (TRIM21) to form K11-linked polyubiquitination chains and mediated lipoma preferred partner (LPP) degradation, which finally promoted the epithelial-mesenchymal transition (EMT) and enhanced the lymphatic metastasis of BCa." (PMID 37422473, 2023).
neuroblastoma (1 paper, 2024). Neuroblastoma (NB) is the most common solid, extracranial childhood tumor. "Also, knockdown of E3 ubiquitin ligase TRIM21 impairs ubiquitination-mediated p21 degradation, reducing the cell viability of human neuroblastoma cells." (PMID 38833095, 2024). "TRIM21 E3 ligase promotes p21 ubiquitination in human neuroblastoma cells." (PMID 38833095, 2024).
non-alcoholic steatohepatitis (1 paper, 2024). "Silencing Trim21 in mice increased HCC oncogenesis in a non-alcoholic steatohepatitis (NASH) context, which was due to overexpression of PD-1 in lymphocytes and PD-L1 in tumors." (PMID 38638430, 2024).
ocular infection (1 paper, 2022). "Therefore, the increased susceptibility of TRIM21 KO mice to HSV-1 replication in the TG, following ocular infection, is not due to changes in type I IFN expression or changes in the levels of IFN-inducible effector molecules OAS1a or tetherin found in the tissue." (PMID 35336995, 2022).
oral cancer (1 paper, 2021). "In this study, we have found that TRIM21 polymorphisms have a strong impact and significant difference on oral cancer susceptibility in men who smoke tobacco and/or chew betel nuts." (PMID 34220328, 2021).
pancreatic ductal adenocarcinoma (1 paper, 2024). An infiltrating adenocarcinoma that arises from the epithelial cells of the pancreas. "TRIM21 mediates the degradation of branched-chain amino acid transaminase 2 (BCAT2) to inhibit the formation and progression of pancreatic ductal adenocarcinoma." (PMID 39154024, 2024).
parasitic infection (1 paper, 2017). "However, at day 7 p.i., corresponding to the time when mice start to succumb to the parasitic infection, TRIM21-deficient mice exhibited significantly decreased levels of RANTES and TNFα; both are induced by the NF-κB-mediated signalling pathway." (PMID 28701773, 2017). "We thus assessed whether TRIM21-mediated ubiquitination of type II Toxoplasma enables restriction of intracellular parasitic infection." (PMID 28701773, 2017).
renal fibrosis (1 paper, 2026). A final common manifestation of a wide variety of chronic kidney diseases characterized by glomerulosclerosis and tubulointerstitial fibrosis. "IFN-γ treatment increased Trim21 expression, reduced Loxl2 expression and renal fibrosis; critically, this protective effect was abolished in tubular-specific Trim21 knockout mice." (PMID 42129148, 2026). "Using tubular cell-specific Trim21 knockout mice, we demonstrated that Trim21 induction protects against ECM accumulation and renal fibrosis." (PMID 42129148, 2026).
serous cystadenoma (1 paper, 2025). A serous neoplasm in which the cysts and papillae are lined by a single layer of cells without atypia, architectural complexity or invasion. "We performed Immunohistochemistry (IHC) analysis on adjacent non‐cancerous and cancerous tissues (n = 60), serous cystadenomas (n = 33) and solid pseudopapillary neoplasms (SPN, n = 26), and the expression of TRIM21 in PC tumor tissues is higher than that in the other three types of tissues." (PMID 39739616, 2025).
Splenomegaly (1 paper, 2025). Abnormal increased size of the spleen. "Compared with WT B6.lpr (Trim21+/+ B6.lpr) mice, Trim21−/− B6.lpr mice showed more severe splenomegaly, lymph node enlargement and renal inflammation as well as albuminuria." (PMID 40610751, 2025). "MRL/lpr mice injected with a Trim21 overexpression vector displayed reduced autoimmune features, including splenomegaly, renal inflammation, circulating anti-dsDNA production and double-negative T cells in the peripheral blood." (PMID 40610751, 2025).
uveal melanoma (1 paper, 2023). A melanoma derived from melanocytes of the uveal tract. "However, high TRIM21 expression levels were observed in LIHC (Liver hepatocellular carcinoma) and UVM (Uveal Melanoma), and elevated TRIM21 was associated with worse OS and PFS in these 2 cancers." (PMID 37335642, 2023).
viral myocarditis (1 paper, 2018). Myocarditis that is caused by an infection with a viral agent. "In vivo overexpression of TRIM21 significantly protected mice against viral myocarditis by suppressing CVB3 replication and reducing cardiac inflammatory cytokine production." (PMID 30410495, 2018). "Treatment with CVB3-infected mice with TRIM21 significantly reduces CVB3 replication in hearts and the severity of viral myocarditis." (PMID 30410495, 2018).